LPL (lipoprotein lipase)
Diseases named in the same sentence as LPL in open-access papers (continued):
Sharing a sentence is not in itself a finding about the gene and the disease.
hypertriglyceridemia (continued). "Zucker rats homozygous for the fa gene are morbidly obese and characterized by fat cell hypertrophy and hyperplasia, increased adipose tissue, lipoprotein lipase activity, hyperinsulinemia, hypertriglyceridemia, and hyperphagia compared to their lean heterozygous counterparts." (PMID 22412960, 2012). "Hematopoietic cell-derived LPL could efficiently ameliorate severe hypertriglyceridemia and hypo-alpha-cholesterolemia at the compensation of increased triglyceride content of liver in LPL-/- mice." (PMID 21980507, 2011). "In conclusion, our results show that hematopoietic cell-derived LPL could ameliorate severe hypertriglyceridemia and hypo-alpha-cholesterolemia, as well as normalize hepatic lipid content even when LPL is absent in muscle and adipose tissue in LPL-/- mice." (PMID 21980507, 2011). "Both Hypertriglyceridemia and dyslipidemia is a common finding in hypertensive patients and therefore LPL gene is considered as a logical candidate gene that could contribute to the development of hypertension." (PMID 19772655, 2009). "On the other hand LPL is an enzyme present in capillary surface, and lack of it causes familial hyperlipoproteinemia type I, characterized by massive hypertriglyceridemia." (PMID 19134193, 2009). "Additionally, SREBP-1c-mediated elevation of apolipoprotein C III also contributes to hypertriglyceridemia through inhibition of lipoprotein lipase, making the degradation of circulatory triglyceride-rich lipoproteins (TrLs) slow down, thus preventing their hepatic clearance." (PMID 41011147, 2025). "In conclusion, the presence of LPL gene mutation should be considered in the presence of type 1 diabetic children and adolescents with no previous dyslipidemia who present with rare severe hypertriglyceridemia, diabetic ketoacidosis, and acute pancreatitis." (PMID 40747209, 2025). "Additionally, apolipoprotein gene expression, particularly that of ApoC-III, may be upregulated by SERMs, contributing to hypertriglyceridemia through the inhibition of lipoprotein lipase." (PMID 40862038, 2025). "However, in hypertriglyceridemia, LPL’s activity is reduced to fewer than five pools per day, resulting in partially delipidated TRL with longer half-life and greater atherogenic potential due to defective hydrolysis perhaps associated to an apoE/apoCIII imbalance." (PMID 40943205, 2025). "VLDL overproduction and the decreased VLDL catabolism due to the low serum lipoprotein lipase (LPL) activity (secondary to low-grade persistent inflammation and insulin resistance) are the principal causes of the increased serum levels of TG-rich VLDL particles and hypertriglyceridemia in MS." (PMID 38732266, 2024). "It is unknown whether the absolute amount of lipids administered, elevations in certain fatty acids within the externally administered triglycerides, or levels of lipoprotein lipase alone are responsible for the development of hypertriglyceridemia or if it is a combination of these factors." (PMID 39394360, 2024). "Additionally, circulating ANGPTL4 induces hypertriglyceridemia by inhibiting LPL." (PMID 39840089, 2024). "However, the mechanisms regulating adipose LPL and its relationship with the development of hypertriglyceridemia are largely unknown." (PMID 38973609, 2024). "A reduction in LPL activity as part of breast cancer therapy combined with additional therapies to reduce hypertriglyceridemia, such as fenofibrate and high‐dose omega‐3 fatty acids, may protect against the hypertriglyceridemia burden; however, this remains to be examined." (PMID 36652113, 2023). "However, in a state of insulin deficiency, lipoprotein lipase is not activated resulting in hypertriglyceridemia." (PMID 36386935, 2022).
hypertriglyceridemia (continued). "In Mexico, hypertriglyceridemia constitutes a health problem in which the genetic bases have been scarcely explored; therefore, our objective was to describe biochemical–clinical characteristics and variants in the APOA5, GPIHBP1, LMF1, and LPL genes in patients with primary hypertriglyceridemia." (PMID 36613909, 2022). "Similarly, hypertriglyceridemia is a commonly observed adverse event with all the immunosuppressants, particularly more so with everolimus, due to its effect of modulation on the expression of lipoprotein lipase." (PMID 35629245, 2022). "Moreover, rituximab was used in a case of severe acquired autoimmune hypertriglyceridaemia resistant to traditional triglyceride-lowering therapies and it was observed to reduce plasma anti-LPL antibody levels and resulted in an improvement of hypertriglyceridaemia." (PMID 36009482, 2022). "Dysfunction of LPL and other factors interacting with LPL may lead to hypertriglyceridemia." (PMID 36051701, 2022). "Moreover, through the inhibition of LPL, it induces hypertriglyceridaemia." (PMID 36009482, 2022). "Therefore, obesity and drinking may jointly affect the process of LPL generation, which is subsequently involved in the pathogenesis of obesity-related hypertriglyceridemia." (PMID 34948819, 2021). "Apolipoproteins (Apo) and angiopoietin-like proteins (ANGPTLs) play a crucial role in regulating LPL activity and recent insights into LPL regulation may elucidate new pharmacological means to address the challenge of hypertriglyceridemia in atherosclerosis development." (PMID 34356847, 2021). "However, in a diabetic state, lipoprotein lipase is not activated or is insufficiently expressed due to insulin deficiency, resulting in hypertriglyceridemia." (PMID 34007967, 2021). "Therefore, low LPL activity leads to hypertriglyceridemia and low HDL levels." (PMID 32849290, 2020). "However, in a diabetic state, lipoprotein lipase is not activated sufficiently due to insulin deficiency resulting in hypertriglyceridemia." (PMID 33396905, 2020). "Thus, we examined the effects of apoC-III synthesis inhibition by volanesorsen on apolipoprotein levels in 2 human intervention trials, 1 in FCS subjects (IONIS1), who lack LPL activity, and 1 in subjects with prominent hypertriglyceridemia (IONIS2) of varied etiology." (PMID 28209220, 2017). "However, in diabetic state, lipoprotein lipase is not activated due to insulin deficiency, resulting in hypertriglyceridemia and hypercholesterolemia (also due to metabolic abnormalities)." (PMID 27313954, 2016). "First, DSS administration increased plasma TG-hydrolysis activity and salt-inhibited TG-hydrolysis activity, that is, LPL activity, by 10–15%, compared with vehicle-treated mice, to an extent similar to those in obese DN-S6K mice, leading to improvement of obesity-related hypertriglyceridemia." (PMID 26268630, 2015). "In addition to hypertriglyceridemia, plasma concentrations of total cholesterol are also elevated in LMF1-/- mice, a likely consequence of diminished catabolism and accumulation of chylomicron particles due to LPL deficiency." (PMID 25302068, 2014). "However, in a diabetic state, lipoprotein lipase is not activated in sufficient amount due to insulin deficiency resulting in hypertriglyceridemia." (PMID 24729889, 2014). "Also, in insulin deficiency, hepatic production of apoprotein B-containing lipoproteins increases and triglycerides cannot be adequately cleared from the plasma due to decreased activity of insulin-dependent lipoprotein lipase (LPL), and this results in hypertriglyceridemia." (PMID 23748069, 2013). "In one study on human LPL-deficient subjects, enhanced glucose-stimulated insulin secretion after an oral glucose tolerance test was found, compared to other groups of non-diabetic patients with hypertriglyceridemia." (PMID 23186339, 2012).
hypertriglyceridemia (continued). "In light of the proatherosclerosis role of macrophage LPL, this raises an issue of whether or not macrophage LPL expressing under the hypertriglyceridemia state further increases the susceptibility of atherosclerosis in LPL-/- mice." (PMID 21980507, 2011). "Acute inflammatory responses, driven by cytokines such as IL-1β, IL-6, and TNF-α, promote hypertriglyceridemia by stimulating hepatic VLDL synthesis and inhibiting lipoprotein lipase-mediated TG clearance." (PMID 41346943, 2025). "Increased concentrations of IL-6 contribute to hypertriglyceridemia and increased LDL cholesterol levels by inhibiting hepatic lipoprotein lipase activity, stimulating triglyceride synthesis, and enhancing lipolysis in adipose tissue." (PMID 40283183, 2025). "Moreover, the group of C apolipoproteins (Apo-C1 and Apo-C3) is involved in the regulation of hepatic uptake of triglyceride-rich lipoproteins (TRL; chylomicrons and VLDL-C) by inhibiting the activity of lipoprotein lipase (LPL), which may result in hypertriglyceridemia." (PMID 40036186, 2025). "Nevertheless, under certain circumstances, TG clearance is delayed, attributed to suboptimal lipoprotein lipase (LPL) activity, excessive hepatic production, or compromised hepatic clearance of TRL, resulting in pathological hypertriglyceridemia (HTG)." (PMID 38841827, 2024). "However, whether MIF regulates LPL and hypertriglyceridemia was previously unknown." (PMID 38973609, 2024). "Fibrates activate peroxisome proliferator‐activated receptor‐α and increase the activity of LPL, and they are also the second‐line medications potentially preventing ASCVD in patients with diabetes and hypertriglyceridemia." (PMID 37448184, 2023). "Severe hypertriglyceridaemia ensues because of delayed catabolism of TRL partly due to severe insulin resistance and, hence, the dampened effect of LPL." (PMID 37233662, 2023). "Fibrates, which are PPAR agonists, are commonly used to treat hypertriglyceridemia, reduce hepatic apoC-III levels, and stimulate lipoprotein lipase-mediated lipolysis." (PMID 38203704, 2023). "Still, other authors observed a lower plasma LPL concentration in patients with CAD, hypertriglyceridemia or metabolic syndrome." (PMID 37686357, 2023). "Hyperchylomicronemia is characterized by the presence of severe hypertriglyceridemia and fasting excess chylomicrons refractory to conventional treatment due to a hereditary defective removal of these particles related to reduced or absent LPL activity or apoCII deficiency." (PMID 36979789, 2023). "GPIGBP1 autoantibody syndrome was found in the patients with multiple sclerosis treated with interferon β1a, who developed severe hypertriglyceridemia and very low plasma levels of GPIHBP1 and LPL." (PMID 37448184, 2023). "Volanesorsen targets mRNA for apoC, the lipoprotein that inhibits LPL, removes hepatic TCL, and contributes to hypertriglyceridemia." (PMID 35371605, 2022). "Activated BAT is characterized by efficient, LPL-dependent disposal of TRL, a metabolic action that is pronounced enough to reverse pathological hypertriglyceridemia." (PMID 35422714, 2022). "Impaired LPL activity leads to the accumulation of chylomicrons and very low-density lipoproteins (VLDL) in plasma, resulting in hypertriglyceridemia." (PMID 34356847, 2021). "Multiple regression analysis indicated that low LPL, high ApoC2, high ApoC3, high ApoE, and high ANGPTL8 levels were the determinants of fasting hypertriglyceridemia." (PMID 34293055, 2021). "We focused on the observation that ANGPTL3 is required by ANGPTL8 to inhibit LPL and the co-expression of ANGPTL3 and ANGPTL8 induces more pronounced hypertriglyceridemia than the overexpression of ANGPTL3 alone." (PMID 34293055, 2021). "Recently, GPIHBP1 auto-antibodies were shown to cause late-onset chylomicronemia by blocking the interaction between LPL and GPIHBP1 in 22 patients with a hitherto unexplained form of acquired hypertriglyceridemia." (PMID 34336854, 2021).
hypertriglyceridemia (continued). "Similarly, there is a familial hypertriglyceridaemia in humans, characterized by an increase in the production of VLDL and apolipoprotein C-II (APOC2) deficiency, in humans is a very rare cause of hyperkylomycinemia, the most common cause is deficiency of lipoprotein lipase (LPL)." (PMID 34665804, 2021). "It is a component of triglyceride-rich lipoproteins (TRLs), a potent inhibitor of lipoprotein lipase (LPL), and delays clearance of TRLs, resulting in hypertriglyceridemia." (PMID 32589506, 2020). "In an insulin-resistant state, hypertriglyceridemia is primarily due to an increased hepatic production of very low density lipoprotein (VLDL) particles, postprandial hyperlipidemia, and low lipoprotein lipase (LPL) levels." (PMID 30200612, 2018). "Angiopoietin-like protein 8(ANGPTL8) and apolipoprotein CIII (apoCIII) were found to inhibit the activity of lipoprotein lipase (LPL) and disrupt the clearance of triglyceride-rich lipoproteins (TRLs), leading to hypertriglyceridemia." (PMID 30021607, 2018). "During acute infections, hypertriglyceridemia can occur due to tumor necrosis factor α (TNF-α) effects on hepatic lipogenesis and lipoprotein lipase." (PMID 30069429, 2018). "At concentrations of 0.25% and 0.5% AI, dose-dependent improvements were observed in the major parameters of hypertriglyceridemia, such as plasma TG, FFA, ApoB, and LPL levels." (PMID 28805698, 2017). "Lipoprotein lipase (LPL) gene knockout heterozygous mice, an animal model of genetic hypertriglyceridemia, exhibited significant insulin resistance, compensatory increased insulin secretion, and ultimately impaired glucose tolerance." (PMID 27034649, 2016). "Such a mechanism would reconcile the coexistence of hypertriglyceridaemia (CM) and increased myocardial TAG-FA metabolism (VLDL) mediated through LPL and VLDL-R uptake mechanisms." (PMID 21773049, 2011). "In dyslipidaemic subjects however, hypertriglyceridaemia is attributed to the prolonged retention of both chylomicrons and VLDL due to inhibited lipolysis of both particles following decreased LPL levels." (PMID 19638239, 2009). "Considering the role of LPL and HL in the lipolysis of plasma VLDL, impaired LPL and HL activities can account for hypertriglyceridemia, and increased VLDL concentrations." (PMID 19709414, 2009). "Hypertriglyceridemia, increases of VLDL-amounts, VLDL-TG and VLDL-CE and reduction of LPL and HL activities are correlated with HD duration." (PMID 19709414, 2009). "Additionally, reduced activity of lipoprotein lipase (LPL) contributes to decreased VLDL degradation, ultimately resulting in hypertriglyceridemia." (PMID 40809436, 2025). "Moreover, hypertriglyceridemia enhances CETP activity and reduces LPL activity, promoting large cholesterol ester-core-depleted HDL particles, which become targets for hepatic lipase, or for endothelial lipases, which hydrolyze TG as well as PLs." (PMID 40298782, 2025). "In them, the overexpression of apoCIII slows down the removal of TG from lipoproteins, decreasing their affinity for lipoprotein lipase (LPL) and reducing the uptake of VLDL and chylomicrons via the hepatic receptor (10-, 12), leading to hypertriglyceridemia in the animals." (PMID 39082576, 2024). "In Gpihbp1–/– mice, LPL is stranded within the interstitial spaces and never reaches the capillary lumen, resulting in severe hypertriglyceridemia." (PMID 39435661, 2024). "Hypertriglyceridemia results from increased secretion of VLDL-rich TGs and decreased hydrolysis of VLDL and chylomicrons in plasma secondary to decreased lipoprotein lipase (LPL) activity." (PMID 39335757, 2024). "Normally, insulin stimulates lipoprotein lipase (LPL; an enzyme that catalyzes the hydrolysis of TG) activity, but in the absence of insulin, LPL cannot be activated, leading to hyperglyceridemia and hypercholesterolemia." (PMID 38629096, 2024).
hypertriglyceridemia (continued). "Decreased LPL expression was also inversely correlated with elevated plasma TG levels, suggesting that adipose PAR2 might regulate hypertriglyceridemia by downregulating LPL." (PMID 38973609, 2024). "Thus, following high-fat diet feeding, PAR2 deficiency attenuated the rise in plasma MIF levels, reversed LPL expression and activity in WAT, and thus corrected hypertriglyceridemia." (PMID 38973609, 2024). "To date, the molecular mechanisms that regulate LPL in WAT and how they contribute to the regulation of hypertriglyceridemia remain unclear." (PMID 38973609, 2024). "Our current study shows that manipulation of LPL in WAT but not in skeletal muscle, liver, or heart is associated with hypertriglyceridemia." (PMID 38973609, 2024). "In mouse models of atherosclerosis regression, conditional knockout of LPL induced hypertriglyceridemia, reflecting increased nascent TRL but not VLDL-C or remnants, and did not affect atherosclerotic burden or morphology." (PMID 34981790, 2022). "The aim of this study was to evaluate the impact of hypercholesterolemia and hypertriglyceridemia on the efficiency of LPL-mediated VLDL lipolysis in subjects with no history of CVD to assess TG-rich lipoprotein metabolism disturbances." (PMID 33917704, 2021). "Fifth, hypertriglyceridemia as a result of lipoprotein lipase inhibition by TNF-α is not usually reported in COVID-19." (PMID 34715834, 2021). "The higher lipoprotein production and lower LPL activity indicate that chylomicron- and very-low-density-lipoprotein (VLDL)-TG in the plasma cannot be hydrolyzed and transported into the tissues, which often results in hypertriglyceridemia." (PMID 33022003, 2020). "Hypertriglyceridemia results from the accumulation of chylomicrons and/or very low-density lipoproteins (VLDL-c), because of the reduction of TG hydrolysis of these lipoproteins by lipoprotein lipase or by the increase in the synthesis of VLDL-c." (PMID 30066825, 2019). "Patients with combined homozygous mutations in the glycosylphosphatidylinositol-anchored high-density lipoprotein–binding protein 1 (GPIHBP1) gene exhibit hypertriglyceridemia and severe CVD, suggesting that LPL-mediated TG clearance is involved in atherosclerosis." (PMID 29738435, 2018). "In the absence of LPL activity, as occurs in FCS, marked accumulation of both VLDL and chylomicrons occurs, resulting in massive hypertriglyceridemia, with TG values often exceeding 2,000 to 5,000 mg/dl, causing acute pancreatitis." (PMID 28209220, 2017). "In the absence of insulin, hypertriglyceridemia normatively occurs given that lipoprotein lipase (LpL) is not activated, an enzyme which is needed to hydrolyze TG." (PMID 29181401, 2017). "On the other hand, upregulation of APOE may lead to hypertriglyceridemia through stimulating the production of VLDL triglyceride in the liver and impairing the LPL-mediated lipolysis." (PMID 27781209, 2016). "In the absence of functional GPIHBP1, LPL is mislocalized within the interstitial spaces, leading to severe hypertriglyceridemia and reduced delivery of lipid nutrients to parenchymal cells." (PMID 26725083, 2016). "Next, to examine whether increased plasma TG-hydrolysis activity improves obesity-related hypertriglyceridemia, we administered either DSS or LPL adenovirus to KK-Ay mice." (PMID 26268630, 2015). "The inhibitory role of AngII, a well-known regulator of blood pressure, on LPL expression in VAT may partly explain the reduction of TG metabolism and resultant hypertriglyceridemia." (PMID 26447765, 2015). "Thus, LPL expression, particularly in WAT, is likely to make an important contribution to decreased plasma TG-hydrolysis activity and the resultant hypertriglyceridemia in SNAT2 mice." (PMID 26268630, 2015). "Thus, the β-adrenergic function of the sympathetic nerve is involved in LPL downregulation in WAT and the resultant hypertriglyceridemia induced by hepatic mTORC1/S6K activation." (PMID 26268630, 2015).